U2AF1 (U2 small nuclear RNA auxiliary factor 1)
Description:
Plays a critical role in both constitutive and enhancer-dependent splicing by mediating protein-protein interactions and protein-RNA interactions required for accurate 3'-splice site selection. Recruits U2 snRNP to the branch point. Directly mediates interactions between U2AF2 and proteins bound to the enhancers and thus may function as a bridge between U2AF2 and the enhancer complex to recruit it to the adjacent intron.
Synonyms: U2AF35; U2AFBP; FP793; RNU2AF1; RN
Tractability: PROTAC: ubiquitination databases record sites on it; its protein half-life has been measured.
Target class: Other nuclear protein
Gene: Protein-coding gene on chromosome 21 (43,092,956 to 43,107,605, reverse strand). Ensembl gene ENSG00000160201.
Subcellular location: Nucleus; Nucleus speckle
Subcellular location (Human Protein Atlas): Nucleoplasm
Pathways (Reactome):
Metabolism of RNA: Transport of Mature mRNA derived from an Intron-Containing Transcript; mRNA 3'-end processing; mRNA Polyadenylation; mRNA Splicing - Major Pathway
Disease: Dengue Virus-Host Interactions
Gene Ontology:
Molecular function: protein binding; RNA binding; pre-mRNA 3'-splice site binding; metal ion binding; nucleic acid binding; RS domain binding
Biological process: mRNA processing; mRNA splicing, via spliceosome; RNA splicing
Cellular component: catalytic step 2 spliceosome; nuclear speck; nucleoplasm; spliceosomal complex; U2AF complex; Cajal body; nucleus
Cancer hallmarks: escaping programmed cell death (promotes); suppression of growth (promotes); proliferative signalling (promotes)
Homologues: Orthologues: dog U2AF1 (100% identical), macaque U2AF1 (100% identical), guinea pig U2AF1 (99% identical), mouse U2af1 (99% identical), pig U2AF1 (99% identical), tropical clawed frog u2af1 (96% identical), zebrafish u2af1 (96% identical), rat U2af1 (93% identical), chimpanzee U2AF1 (88% identical), Drosophila melanogaster U2af38 (80% identical), Caenorhabditis elegans uaf-2 (66% identical). Paralogues in human: U2AF1L4 (60% identical), ZRSR2 (41% identical).
Diseases named in the same sentence as U2AF1 in open-access papers:
U2AF1 is named in the same sentence as 66 diseases in open-access papers, as found by Europe PMC text mining. Sharing a sentence is not in itself a finding about the gene and the disease. The quoted sentences say what the papers report.
myelodysplastic syndrome (74 papers, 2012 to 2026). A clonal hematopoietic disorder characterized by dysplasia and ineffective hematopoiesis in one or more of the hematopoietic cell lines. "U2 small nuclear RNA auxiliary factor 1 (U2AF1) regulates the RNA splicing during gene expression, and its mutations are often observed in myelodysplastic syndrome, primary myelofibrosis and other solid tumors." (PMID 41153010, 2025). "Recurrent somatic mutations in the spliceosome genes SF3B1, SRSF2, and U2AF1 are frequently identified in patients with myeloid neoplasms, such as myelodysplastic syndromes." (PMID 40386435, 2025). "Mutations in the U2AF1 gene have been described in a wide range of cancers, including myelodysplastic syndrome, acute myeloid leukaemia, primary myelofibrosis, chronic myelomonocytic leukaemia, hairy cell leukaemia and various solid tumours." (PMID 40066790, 2025). "U2AF1 mutations are more common in younger patients with myelodysplastic syndromes (MDS) and, despite remaining stable throughout clinical progression, are linked to a poorer prognosis." (PMID 38601162, 2024). "U2AF1 mutation is a genetic driver event in the initiation of myelodysplastic syndromes (MDSs) and frequently occurs in myeloid malignancies." (PMID 36139566, 2022). "As a recognized early driver of myelodysplastic syndromes (MDSs), U2AF1 mutates most frequently in MDS, followed by acute myeloid leukemia (AML) and myeloproliferative neoplasms (MPNs)." (PMID 36139566, 2022). "U2AF1 mutation at S34F promotes autophagic flux by activating FOXO3a, thereby mediating myelodysplastic syndrome progression." (PMID 35526025, 2022). "The U2AF1 gene is a core part of mRNA splicing machinery and frequently contains somatic mutations that contribute to oncogenesis in myelodysplastic syndrome, acute myeloid leukemia, and other cancers." (PMID 35041928, 2022). "For example, subsets of alternatively spliced genes found in aging, with mutations in the spliceosome gene U2AF1 in myelodysplastic syndrome and with differentiation of erythroblasts, are enriched for genes involved in RNA processing." (PMID 32660516, 2020). "This study reveals a novel, to our knowledge, connection between the splice factor U2AF1 mutation responsible for myelodysplastic syndrome and ribosome biogenesis." (PMID 33137094, 2020). "Among these factors, SF3B1, SRSF2, and U2AF1, are most frequently mutated in patients with myelodysplastic syndrome (MDS), and also commonly occurred in clonal hematopoiesis, acute myeloid leukemia (AML), CLL, and a variety of solid tumors." (PMID 32481522, 2020). "U2AF1 has been implicated in the altered splicing events in lung tumors, myelodysplastic syndrome and other hematological malignancies." (PMID 33261069, 2020). "Even a single amino acid mutation of U2AF1 can cause serious disease such as certain cancers or myelodysplastic syndromes." (PMID 32958768, 2020). "U2AF1 is frequently mutated in cancers, particularly in myelodysplastic syndromes, along with other mutated splicing factors." (PMID 30916337, 2019). "Mutation of the spliceosome components SF3B1 and U2AF1 are recurrent driver events in many cancer types including chronic lymphoblastic leukemia, myelodysplastic syndrome, uveal melanoma and breast cancer." (PMID 28177281, 2017). "Recently, somatic mutations in U2AF1 were discovered in myelodysplastic syndrome (MDS) and mainly occurred in two codons (Ser34 and Q157)." (PMID 23029227, 2012). "Recurrent, heterozygous and mutually exclusive mutations of splicing factors SF3B1, SRSF2 and U2AF1 frequently occur in blood and solid cancers (for instance in myelodysplastic syndromes, chronic lymphocytic leukaemia, acute myeloid leukaemia, uveal melanoma and breast cancer)." (PMID 36855776, 2023). "Notably, KD of U2AF1 had this effect in both K562 and HepG2 cells, and mutations in U2AF1 in myelodysplastic syndromes are associated with reduction of Pol2 pause release and R loop accumulation." (PMID 35362230, 2022).
myelodysplastic syndrome (continued). "Deregulation of U2AF1 is observed in lung carcinoma, and it is mutated in myelodysplastic syndrome." (PMID 29805743, 2018). "We have previously recognized the genotypic and prognostic heterogeneity of U2AF1 mutations (MT) in myelofibrosis (MF) and myelodysplastic syndromes (MDS)." (PMID 37735430, 2023). "Mutations in the U2 small nuclear RNA auxiliary factor 1 (U2AF1) gene are the common feature of a major subset in myelodysplastic syndromes (MDS)." (PMID 34183647, 2021). "U2AF1 frequently acquires an S34F-encoding mutation among patients with myelodysplastic syndromes (MDS)." (PMID 32343311, 2020). "Recently, somatic mutations in U2AF1 have been recurrently observed in several human neoplasms, including myelodysplastic syndrome (MDS), acute myeloid leukemia (AML), and lung cancers." (PMID 31836708, 2019). "Mutations of the splicing factor–encoding gene U2AF1 are frequent in the myelodysplastic syndromes (MDS), a myeloid malignancy, and other cancers." (PMID 28436936, 2017). "Somatic mutations of U2AF1 gene have recently been identified in myelodysplastic syndrome (MDS) and acute myeloid leukemia (AML)." (PMID 23029227, 2012). "Such mutations, including hotspots in SF3B1 and U2AF1 and loss-of-function events in FUBP1, RBM5, RBM10, and ZRSR2, are recurrent in myelodysplastic syndromes, acute myeloid leukemia, chronic myelomonocytic leukemia, and multiple solid tumors 8,42–45." (PMID 41279721, 2025). "We demonstrated this in the context of myelodysplastic syndromes (MDS), where mutations in splicing factors (SF) genes such as U2AF1 are prevalent in approximately 50% of patients and linked to decreased survival rates." (PMID 40623970, 2025). "Spliceosome mutations, such as those in SF3B1, SRSF2, U2AF1, and ZRSR2, are commonly found in myeloid neoplasms like myelodysplastic syndromes (MDSs) and other MPNs." (PMID 40507313, 2025). "Mutations in RNA splicing factor genes including SF3B1, U2AF1, SRSF2, and ZRSR2 have been reported to contribute to development of myeloid neoplasms including myelodysplastic syndrome (MDS) and secondary acute myeloid leukemia (sAML)." (PMID 38883705, 2024). "S34F/Y substitution in the Zinc finger 1 domain of U2AF1 has been detected in approximately 12% of patients with myelodysplastic syndromes (MDSs), a group of disorders characterized by the abnormal formation and function of blood cells." (PMID 37511171, 2023). "In myelodysplastic neoplasms (MDS), the 20q deletion [del(20q)] is a recurrent chromosomal abnormality that it has a high co‐occurrence with U2AF1 mutations." (PMID 37403747, 2023). "Mutations in splicing factors U2AF1 and SRSF2, which are associated with myelodysplastic syndrome (MDS), have been linked to R-loops and have functional incapacitation variants in SF3B1 in a zebrafish model." (PMID 37894353, 2023). "In fact, mutations in U2AF1, SF3B1, and SRSF2 genes are frequently found in patients affected by myelodysplastic syndromes (MDSs), which are myeloid cancers typical of the elderly." (PMID 38132139, 2023). "Prevalent U2AF1 somatic mutations, including U2AF1S34F, occur in hematopoietic malignancies including myelodysplastic syndrome (MDS), AML, and chronic myelomonocytic leukemia (CMML), as well as in some solid tumors such as lung adenocarcinoma." (PMID 35585060, 2022). "Recurrent somatic mutations of the SFG, such as SF3B1, SRSF2, U2AF1, and ZRSR2, have been uncovered in myelodysplastic syndrome (MDS), chronic lymphocytic leukemia, acute myeloid leukemia, breast cancer, lung adenocarcinoma, and uveal melanoma." (PMID 36684432, 2022).
myelodysplastic syndrome (continued). "In Myelodysplastic Syndromes (MDS), caused by splicing factor mutations in components such as SRSF2 and U2AF1, aberrant R-loop accumulation is linked to the compromised proliferation of bone-marrow-derived blood progenitors, a characteristic feature of MDS." (PMID 36553448, 2022). "U2AF1 and SF3B1, the core components of spliceosomes, are frequently mutated in cases of myelodysplastic syndrome (MDS) and several types of solid tumor." (PMID 33397462, 2021). "Alterations in SF3B1 were initially discovered in myelodysplastic syndromes (MDSs) and chronic lymphocytic leukemia (CLL), together with other mutations of splicing factors, such as U2AF1, SRSF2 and ZRSR2 (refs 1, 2, 3)." (PMID 26842708, 2016). "We report a rare case of acquired SPTB spherocytosis coinciding with a myelodysplastic syndrome associated U2AF1 mutation, neither found in germline DNA." (PMID 35720514, 2022). "In addition, mutations in U2 small nuclear RNA auxiliary factor 1 (U2AF1) or Wilms’ tumor suppressor gene 1 (WT1) are associated with poor survival of patients with AML and myelodysplastic syndromes." (PMID 35526025, 2022). "Mutations in U2AF1 and SRSF2 affect the spliceosome and are frequently found in antecedent hematological disorders, such as myelodysplastic syndrome (MDS) and myeloproliferative neoplasms (MPN), as well as are mutations in chromatin regulating genes ASXL1 and BCOR." (PMID 33509276, 2021). "It had been clearly demonstrated that mutant U2AF1 could induce AS and alter expression of crucial genes and in turn lead to myelodysplastic syndromes." (PMID 33274830, 2020). "Mutations in LUC7L2, PRPF8,SF3B1, SRSF2, U2AF1, and ZRSR2 genes occur at various frequencies ranging between 40% and 85% in different subtypes of myelodysplastic syndrome (MDS) and 5% and 10% of acute myeloid leukemia (AML) and myeloproliferative neoplasms (MPNs)." (PMID 31766606, 2019). "In hematological tumors, more than half of patients with myelodysplastic syndromes (MDS) show mutations in functional components of the spliceosome, commonly in serine-rich SFs, such as SF3B1, SRSF2, and U2AF1." (PMID 36611187, 2023). "Additionally, mutant U2af1 combined with Tet2-deficiency does not suffice to initiate myelodysplastic syndrome." (PMID 34203454, 2021). "Genes of the spliceosome-complex including SRSF2, SF3B1, U2AF1, and ZRSR2 are frequently mutated in myeloid malignancies such as AML, myelodysplastic syndromes (MDS) or myeloproliferative disorders." (PMID 33692956, 2021). "Studies have shown that in myelodysplastic syndrome (MDS) SRSF2 was mutated in 12–14% of the cases and mutations in U2AF1 occur in 15% of the MDS cases." (PMID 31426461, 2019). "Notably, the critical role of mutations in epigenetic regulators and splicing factors, such as ASXL1, SRSF2 and U2AF1, in impaired hematopoiesis and the development of myelodysplastic syndromes (MDS), was validated in preclinical and clinical studies." (PMID 37444441, 2023). "The patient recovered quickly after splenectomy, which confirms that his myelodysplastic syndrome (MDS)-associated U2AF1 mutation did not affect the clinical picture." (PMID 35720514, 2022). "Studies revealed that there are also mRNA splicing events, particularly in SF3B1, U2AF1, and SRSF2, in hematological tumors such as chronic lymphocytic leukemia (CLL) and myelodysplastic syndrome (MDS)." (PMID 31798590, 2019). "Myeloid gene mutations: RUNX1 44.14%, U2AF1 40.74%, PHF6 (c.663_668clclims13) 6.3%, PHF6 (c.725G>A) 73.26%; myelodysplastic syndrome (MDS)-FISH were all negative." (PMID 38457569, 2024).
acute myeloid leukemia (34 papers, 2012 to 2026). Acute myeloid leukemia (AML) is a group of neoplasms arising from precursor cells committed to the myeloid cell-line differentiation. "On average, U2AF1 mutations are found in 1.5% of all cancers; the most common types are acute myeloid leukemia, colon cancer, and lung cancer." (PMID 36251702, 2022). "The importance of the spliceosome machinery in leukemogenesis has been demonstrated and mutations in U2AF1 were recently shown to predict poor prognosis in patients with de novo acute myeloid leukemia." (PMID 27602765, 2016). "Interestingly, in humans, a mutation in U2AF1 was associated with hematopoietic stem cell disorders that can progress into acute myeloid leukemia, and this mutation was shown to cause missplicing events as a result to alterations in preferred 3’SS, which are presumed to be related with the disease." (PMID 34570750, 2021). "We performed comprehensive analysis for prognostic significance of U2AF1 mutations in acute myeloid leukemia (AML) cohort based on The Cancer Genome Atlas (TCGA) database." (PMID 34183647, 2021). "The patient was diagnosed with acute myeloid leukemia (FLT3, DNMT3A, U2AF1, and SMC3 mutations; KMT2A amplification; high-risk) and adenocarcinoma of the cardia." (PMID 39121277, 2024). "In the present case, the final diagnosis was acute myeloid leukemia (FLT3, DNMT3A, U2AF1, and SMC3 mutations; KMT2A amplification; high-risk) with adenocarcinoma of the cardia." (PMID 39121277, 2024). "Among patients with U2AF1 gene mutations, those with ASXL1 mutations were prone to develop into acute myeloid leukemia, those with RUNX1 mutations had an increased risk of relapse, and those with TET2 mutations had higher 1-year survival rate." (PMID 33122737, 2020). "To determine how the engineered U2AF1 S34F allele affects mRNA splicing, we first assayed the inclusion levels of 20 cassette exons that were previously reported to be associated with mutant U2AF1 in both LUAD and AML (acute myeloid leukemia)." (PMID 27776121, 2016). "Using RNA-Seq data from 182 lung adenocarcinomas and 167 acute myeloid leukemias (AML), in which U2AF1 is somatically mutated in 3–4% of cases, we identified 131 and 369 splicing alterations, respectively, that were significantly associated with U2AF1 mutation." (PMID 24498085, 2014). "In the current study, we considered 179 U2AF1-mutated patients with clonal cytopenia of undetermined significance (CCUS; n = 22), MDS (n = 108), MDS/acute myeloid leukemia (AML; n = 18) and AML (n = 31)." (PMID 37735430, 2023). "A third cancer-associated mutated splicing component is U2AF1, which is recurrently mutated in myelodysplasia syndromes (MDS, ~9%) and hematological malignancies such as chronic myelomonocytic leukemia (CMML, ~8%) and acute myeloid leukemia (AML, ~4%)." (PMID 35053445, 2022). "Mutations in U2AF1 are present in patients with MDS (in approximately 11% of cases), myeloproliferative neoplasms (MPN), clonal hematopoiesis of indeterminate potential (CHIP), acute myeloid leukemia (AML, in about 4% of patients), chronic lymphocytic leukemia (CLL), and a variety of solid tumors." (PMID 34203454, 2021).